HFE (homeostatic iron regulator)
Diseases named in the same sentence as HFE in open-access papers (continued):
Sharing a sentence is not in itself a finding about the gene and the disease.
hemochromatosis (continued). "Cognitive impairment in the elderly may be associated with genetic factors such as polymorphisms in apolipoprotein E allele (ApoE4 variants) and hemochromatosis gene (HFE C282Y variant)." (PMID 35162428, 2022). "Additionally, hepcidin is highly dependent on transferrin receptor 2 (TfR2) and hereditary hemochromatosis protein (HFE), a human homeostatic iron regulator protein encoded by the HFE gene." (PMID 35052868, 2022). "In hereditary hemochromatosis, mutations in genes such as HFE, TFR2, HJV, HAMP cause a hepcidin deficiency due to the reduced activity of the hepatic BMP-SMAD-signaling pathway or hepcidin synthesis per se, resulting in increased iron adsorption and iron release into the bloodstream." (PMID 35204362, 2022). "Hemochromatosis is a metabolic disorder caused by mutations in the HFE gene." (PMID 36064805, 2022). "HFE mutations can be found in over 80% of patients with hemochromatosis." (PMID 35453939, 2022). "Most forms of hemochromatosis cause injury in peripheral tissues (heart and liver), however, it should be noted that the principal variants of the HFE gene can affect brain iron homeostasis and is considered as a risk factor for neurodegenerative disorders, particularly Parkinson’s disease." (PMID 35185447, 2021). "The low expression level of Hepcidin is usually seen whether there is mutation in HAMP gene or a gene named Hemochromatosis (HFE), that codes for HFE protein in case of HFE disease (Le Gac & Férec, 2005)." (PMID 32588561, 2020). "The homeostatic iron regulator HFE (hemochromatosis) mutation, which has been shown to affect iron absorption and iron overload, is hypothesized to be related to lead intoxication in vulnerable individuals." (PMID 30691187, 2019). "HFE gene mutation might cause hemochromatosis which is a disease characterized by iron accumulation in the body, especially in the liver." (PMID 30661508, 2019). "In these individuals absorption of both inorganic and heme iron is increased because basolateral efflux of iron from the enterocytes is inappropriately regulated; most importantly hepcidin levels are very low in patients with hemochromatosis type 1 (mutation of the HFE gene, MIM #235200)." (PMID 27363994, 2016). "Moreover, hemochromatosis is a common inherited iron overload disorder due to mutations at C282Y and H63D in the HFE (hemochromatosis Fe) gene." (PMID 24401005, 2014). "Mutations in HFE gene (the hemochromatosis gene) are one cause of hemochromatosis." (PMID 24904420, 2014). "Hemochromatosis is the genetic form of iron load in which patients lack a functional HFE protein involved in iron homeostasis due to mutations in the HFE gene that may also influence lead absorption." (PMID 21912545, 2011). "However, about 1 to 2 percent of individuals with compound heterozygous HFE mutations appear to be at risk for hemochromatosis." (PMID 16824219, 2006). "Hemochromatosis is most often caused by mutations in the gene HFE on chromosome 6p21.3." (PMID 16824219, 2006). "Hemochromatosis occurs in 0.003 – 0.005 of persons of northwestern European descent, and is typically associated with homozygosity for the C282Y mutation of the HFE gene (exon 2, nt 845 G→A), located ~4 Mb telomeric to the human leukocyte antigen (HLA) region on Ch6p." (PMID 16042809, 2005). "In addition, epigenetic mechanisms may play an important role since, e.g., maternal hemochromatosis gene (HFE) genotypes have been associated with increased risk of type 1 diabetes." (PMID 33805588, 2021). "Hemochromatosis, a well-known blood disease, has a very clear genetic basis in its manifestation and progression and is often the result of many different potential mutations to different genes with the most common mutation being the C282Y mutation of the HFE gene." (PMID 22151998, 2011).
hemochromatosis (continued). "The GWAS of UK Biobank uncovered that 30 genetic loci were associated with VVs; the strongest associations found three SNPs in the CASZ1, PIEZO1, and 50 kB upstream to the HFE (hemochromatosis) genes." (PMID 39858587, 2024). "The human hemochromatosis high-FE2+ (HFE) gene, linked to the major histocompatibility complex (MHC) on chromosome 6p, encodes the MHC class-I-like protein HFE that binds beta-2 microglobulin." (PMID 38473913, 2024). "The Homeostatic Iron Regulator (HFE) gene (the hemochromatosis gene) is responsible for transporting and regulating iron in the brain." (PMID 38790243, 2024). "Different hemochromatosis proteins are involved in Hepc regulation: hereditary hemochromatosis protein (HFE), Transferrin receptor type 1 and 2 (TfR1 and TfR2), Hemojuvelin (Hjv), bone morphogenetic protein (BMP)." (PMID 38913042, 2024). "Mutations in human HFE and TFR2 genes cause Hemochromatosis type 1 and 3, respectively, a genetic heterogeneous disease that results in body iron accumulation due to abnormally low Hepc production." (PMID 39273097, 2024). "Approximately 82–90% of clinical disease in Caucasian HH patients is related to homozygosity for the missense variant C282Y of the homeostatic iron regulator gene (HFE gene), referred to as hemochromatosis type 1 or HFE hemochromatosis." (PMID 34067164, 2021). "Hepcidin and hemochromatosis (HFE) are iron regulatory proteins that are encoded by HAMP and HFE genes." (PMID 32588561, 2020). "The HFE (hemochromatosis) gene, reported about two decades ago —which was found in patients with hereditary hemochromatosis (HH)—is an autosomal recessive genetic disease producing an increase in the absorption of ingested iron." (PMID 30691187, 2019). "HFE hemochromatosis (often classified as type 1; OMIM #235200) is associated with mutations in the HFE gene and constitutes the most frequent form of hereditary hemochromatosis, with high prevalence in populations of Northern European ancestry." (PMID 30420953, 2018). "Rs1853021 in LPA and rs2802292 in FOXO3 (p = 0.052) and rs1800562 in HFE (hemochromatosis) and rs56354395 in ADIPOQ (adiponectin, C1Q and collagen domain containing) (p = 0.059)." (PMID 28206976, 2017). "In these cases, hemochromatosis is diagnosed on the basis of the genetic analyses (homozygosity for C282Y in the HFE gene), as the changes in iron metabolism in the advanced stage of any cirrhosis resemble those seen in early hemochromatosis." (PMID 27590261, 2016). "In the Hemochromatosis and Iron Overload Screening Study of adult primary care participants in North America, 8.5% of 176 HFE C282Y homozygotes and 10.9% of 312 HFE wt/wt controls reported taking thyroid supplements (p = 0.4019)." (PMID 26504855, 2015). "For example, the product of the HFE gene, hemochromatosis protein, is involved in the regulation of iron absorption." (PMID 23467907, 2013). "HFE protein (gene responsible for hemochromatosis) interacts with TfR1 at the level of cells from intestinal crypts and tissue macrophages." (PMID 24146699, 2013). "Human hemochromatosis protein (HFE), the protein incriminated in the pathogenesis of hemochromatosis, competes with transferrin for binding to the receptor, thereby impeding the uptake of iron from transferrin." (PMID 23578325, 2013). "The hereditary hemochromatosis protein, HFE, which is responsible for type 1 hemochromatosis, was identified over 15 years ago." (PMID 22581367, 2013). "HFE is a positive modulator of Hamp transcription, which, when defective, leads to hemochromatosis (HH) in humans and a HH-like phenotype in knockout animal models." (PMID 22581367, 2013). "Recent studies with animal models of hemochromatosis suggest an important role of HFE protein as an iron sensor and upstream regulator of hepcidin in hepatocytes." (PMID 21687645, 2011). "Five white women were previously diagnosed to have hemochromatosis, homozygosity for HFE C282Y, and iron overload phenotypes." (PMID 21176208, 2010).
hemochromatosis (continued). "Frequencies of the most common haplotypes detected in HFE C282Y homozygotes with a hemochromatosis phenotype from this geographic area were compared with corresponding frequencies in control subjects." (PMID 16042809, 2005). "Three genes are currently believed to play a role in lead neurotoxicity: the ALAD gene, which codes for δ-aminolevulinic acid dehydratase; the vitamin D receptor (VDR) gene; and the hemochromatosis gene coding for a defective protein known as HFE." (PMID 15198918, 2004). "As individuals with variants in hemochromatosis genes, HFE or HJV, (and no other gene) accounted for 137 individuals (45.5%) these were deprioritised." (PMID 41372986, 2025). "In 7 patients heterozygous variants in the HFE gene were detected, which are not known to be associated with increased risk of hemochromatosis, namely H63D in 3 patients, C282Y in 3 patients and in S65C in 1 patient." (PMID 39309680, 2024). "We studied the height of adults with hemochromatosis genotype HFE p.C282Y/p.C282Y and without common HFE mutations (wt/wt)." (PMID 37930135, 2024). "Initial hemochromatosis mutation analysis showed neither of the 2 alleles of the HFE gene contained the C282Y or H63D pathogenic variants." (PMID 39450139, 2024). "Mutation analysis of the HFE (homeostatic iron regulator) gene responsible for hereditary hemochromatosis was negative for a homozygous mutation." (PMID 38186413, 2023). "In clinical settings, HFE mutation analysis in children is not recommended unless they have iron phenotypes suggestive of hemochromatosis or iron overload." (PMID 38186421, 2023). "We aimed to estimate hemochromatosis genotype associations with brain MRI measures and incident dementia in the UKB community genotyped cohort, with a specific focus on male HFE p.C282Y homozygotes, who develop the majority of hemochromatosis related physical diseases." (PMID 33427739, 2021). "However, median Tsat in different genotypes was 32–46% and a consistent Tsat of above 26% and 23% was found in HFE wildtype men and women, respectively, in a Norwegian hemochromatosis screening which comprised around 65,000 volunteers." (PMID 34440336, 2021). "This variation in the HFE gene is associated with the mild form of hemochromatosis and accounts for 7.8% of HH cases that were neither C282Y nor H63D substitutions." (PMID 35185447, 2021). "The HFE gene encodes the α chain of the MHC class-I like molecule that associates with the β-2-microglobulin chain, and HFE gene defects are the primary cause of hereditary iron overload (hemochromatosis) in humans." (PMID 31108902, 2019). "As hemochromatosis can also be caused by other mutation in the HFE gene or so called non-HFE hemochromatosis genes (HJV, HAMP, TFR2), homozygosity for p.Cys282Tyr is neither sufficient nor necessary for the diagnosis hemochromatosis." (PMID 30514216, 2018). "Thus, HFE hemochromatosis patients and Hfe−/− mice express inappropriately low hepcidin levels and exhibit blunted hepcidin responses to iron intake due to defective BMP/SMAD signaling." (PMID 30420953, 2018). "The current study examined the association between hemochromatosis genotypes and oral cancer risk, and the results indicate that HFE polymorphisms are not a risk factor for oral cancer in Whites and Blacks." (PMID 26690219, 2015). "It does so mainly by interacting with hemochromatosis (HFE) protein." (PMID 26611327, 2015). "Additionally, disrupting the function of the β2-M/hemochromatosis (HFE) complex by HFE knockdown was sufficient to reverse β2-M-mediated EMT in the HK-2 cells." (PMID 25899529, 2015). "Although those who are heterozygous for the C282Y mutation of the HFE gene do not usually express a hemochromatosis phenotype, 90–100% of typical hemochromatosis patients are homozygous for the C282Y mutation." (PMID 26197432, 2015).
hemochromatosis (continued). "The effect of the HFE gene C282Y mutation of hemochromatosis in the occurrence of non-transfusional iron overload in patients with beta-thalassemia has been controversial." (PMID 25330520, 2014). "To assess the relevance of the cellular location of iron deposition at the time of infection, we used HFE-deficient mice which are used as a model of human hemochromatosis and accumulate iron in parenchymal cells rather than inside macrophages." (PMID 23459556, 2013). "A hemochromatosis was possible in view of a high ferritin and a transferrin saturation level > 45%, but this alone does not explain the appearance of fulminant hepatitis (a mutation of the HFE gene was not sought)." (PMID 37457563, 2023). "While the simulation differs slightly from the experiment, by causing hemochromatosis through mutation in the HAMP gene (hemochromatosis type 2B) rather than through the HFE gene (hemochromatosis type 1), the results are qualitatively similar to the experiments." (PMID 30608934, 2019). "Finally, we did not evaluate HFE mutation to rule out hereditary hemochromatosis; this was not essential because hereditary hemochromatosis is very rare in Japan (i.e., the prevalence of the C282Y mutation is 0.000039% among Asians)." (PMID 30044835, 2018). "Mutation analysis of the HFE gene is helpful to confirm the diagnosis but utility may be limited if the hemochromatosis is not due to an HFE mutation." (PMID 26136783, 2015). "Additionally, evidence indicates that the hemochromatosis gene HFE might be required for the synthesis of hepcidin." (PMID 21687645, 2011). "However, at least for M. tuberculosis infection, the defect of B2m−/− mice may be due to iron overload or hemochromatosis, as β2-microglobulin associates with the MHC I family member HFE, which is involved in iron homeostasis." (PMID 19730693, 2009). "A follow-up hereditary hemochromatosis genetic panel analyzed FTH1, FTL, HAMP, HFE, HJV, SLC40A1, and TFR2 genes." (PMID 39450139, 2024). "Hemochromatosis excludes the acquired iron overload, and it is caused by mutations in the five main genes; however, it is more frequently associated with the p.Cys282Tyr (C282Y) homozygous genotype, which is the most common genetic alteration associated with hemochromatosis, in the HFE gene." (PMID 35052458, 2022). "Iron metabolism characteristics of Hfe knockout (Hfe−/−) mice are inherited as autosomal recessive traits and are typical of HFE hemochromatosis, but iron metabolism characteristics of different Hfe−/− mouse strains vary." (PMID 28331855, 2017). "HH involves an underlying dysregulation of one of the several iron-controlling genes which can be divided into hemochromatosis gene (HFE) related or non-HFE related hemochromatosis." (PMID 39578337, 2025). "Initial laboratory testing revealed elevated iron saturation and iron levels, prompting a presumptive diagnosis of hemochromatosis; however, this was later ruled out due to negative homeostatic iron regulator protein (HFE) gene testing." (PMID 41441537, 2025). "While initial evaluation for hemochromatosis was appropriate, a broader differential diagnosis was not pursued after negative HFE gene testing." (PMID 41441537, 2025). "The liver biopsy revealed findings suggestive of early-stage hemochromatosis due to periportal intracellular iron deposition, though the patient lacked the HFE gene." (PMID 39677093, 2024). "We found an association between a diplotype covering the homeostatic iron regulator (HFE) gene and hemochromatosis, even though the well-known causal SNP was not directly genotyped or imputed." (PMID 38905121, 2024). "Characteristics of cohorts of individuals aged ≤17 years with homeostatic iron regulator (HFE) p.C282Y (rs1800562) homozygosity, a common hemochromatosis genotype, have not been reported." (PMID 38186421, 2023).
hereditary hemochromatosis (93 papers, 2005 to 2026). An inherited metabolic disorder characterized by iron accumulation in the tissues. "Hereditary hemochromatosis (HH) is an example of primary IO, caused by the mutation of the HFE gene, leading to hepcidin deficiency." (PMID 41596552, 2026). "The c.845G>A (p.Cys282Tyr) variant in the HFE gene, responsible for hereditary hemochromatosis, was the most common (4 carriers), while the c.2304dup (p.Met769Hisfs*26) variant in the ATP7B gene was identified in one individual." (PMID 40699671, 2025). "HFE gene mutations causing aberrant iron metabolism are the pathophysiologic hallmark of hereditary hemochromatosis (HH)." (PMID 39568488, 2024). "This case highlights the clinical presentation and management of porphyria cutanea tarda (PCT) in a 34-year-old woman with previously undiagnosed hereditary hemochromatosis (HH) due to homozygous C282Y HFE mutation." (PMID 39568488, 2024). "Hereditary hemochromatosis (HH) is an autosomal recessive disorder characterized by excess iron absorption in the body following a mutation in the HFE gene." (PMID 38361672, 2024). "Hereditary hemochromatosis (HH) involves iron overload due to HFE protein mutations, while atrial fibrillation (AF) is characterized by irregular heart rhythms." (PMID 38333328, 2024). "Further testing for HFE gene mutations revealed simple heterozygote C282Y status, confirming the diagnosis of hereditary hemochromatosis." (PMID 38361672, 2024). "Hereditary hemochromatosis is primarily caused by mutations in the homeostatic iron regulator (HFE) gene, which is closely linked to the HLA-A locus on chromosome 6p." (PMID 39171001, 2024). "Hereditary hemochromatosis results from homozygosity for an HFE protein mutation, leading to increased iron absorption." (PMID 39171001, 2024). "Mutations in the HFE gene impair the production of the principal iron hormone hepcidin, resulting in iron accumulation in various tissues and the development of hereditary hemochromatosis (HH)." (PMID 37240294, 2023). "Hereditary hemochromatosis is an autosomal recessive condition with incomplete penetrance that is most commonly caused by a mutation in the HFE gene." (PMID 37539416, 2023). "Mutations in the HFE/Hfe gene cause Hereditary Hemochromatosis (HH), a highly prevalent genetic disorder characterized by elevated iron deposition in multiple tissues." (PMID 37240294, 2023). "Further testing for mutations in the HFE gene given elevated ferritin was performed and returned positive, which confirmed the diagnosis of adult-onset hereditary hemochromatosis." (PMID 37539416, 2023). "Hereditary hemochromatosis is an iron-overload disease most often arising from a mutation in the Homeostatic Fe regulator (HFE) gene." (PMID 36512071, 2023). "The HFE gene encodes for a protein involved in iron metabolism, while genetic variants in HFE have been associated with hereditary hemochromatosis (HH), an iron overload disorder." (PMID 34570359, 2022). "The presence of a risk genotype of the HFE gene (diagnosis of hereditary hemochromatosis) was also assessed." (PMID 35445529, 2022). "The haemochromatosis gene HFE encodes the major histocompatibility complex (MHC) class-1like protein HFE that binds beta-2 microglobulin." (PMID 35705926, 2022). "The most frequent type of hereditary hemochromatosis (HH), an endocrine disorder of iron overload, is associated with mutations in the HFE gene." (PMID 34570359, 2022). "MyCode currently includes screening and return of results for the ACMG secondary findings list, version 2 (also known as ACMG SF v2), along with the HFE gene C282Y variant associated with hereditary hemochromatosis." (PMID 35629115, 2022). "Hereditary hemochromatosis (HH) is an autosomal recessive genetic disorder due to mutations of the homeostatic iron regulator (HFE) gene (located on the short arm of chromosome 6)." (PMID 36721599, 2022).